C3 (complement C3)
Diseases named in the same sentence as C3 in open-access papers (continued):
Sharing a sentence is not in itself a finding about the gene and the disease.
endometriosis (20 papers, 2013 to 2025). The growth of functional endometrial tissue in anatomic sites outside the uterine body. "In fact, serum levels of C3 are elevated in patients with endometriosis and C3 was proposed as a potential diagnostic biomarker." (PMID 39935459, 2025). "Properdin is secreted by monocytes, macrophages, and T lymphocytes and, in the endometrium, increases the proliferation of endometrial cells and has been implicated in endometriosis via its upregulation of C3." (PMID 41155459, 2025). "In this article we describe the potential value as diagnostic markers for endometriosis of two proteins (serum albumin and complement C3 precursor), previously identified as differentially expressed in women with endometriosis respect to healthy control by 2D gel analysis." (PMID 26759817, 2015). "Our results indicate that the biomarker and therapeutic potential of C3 should be studied in endometriosis in more depth." (PMID 40698088, 2025). "C3 seems pivotal to endometriosis pathology, and given its strong upregulation and presence both in tissue and well in peritoneal fluid of endometriosis sufferers, it poses an interesting target for early diagnosis and therapy." (PMID 40698088, 2025). "Our results present a similar picture; complement C3 as well as the JAK/STAT3 pathway seems to play a role in the development of endometriosis." (PMID 40698088, 2025). "C3, a major effector at which all complement pathways converge, was one of the most differentially expressed genes in endometriosis." (PMID 40698088, 2025). "Among the various components of the complement system, complement component 3 (C3) has been the most extensively studied in the context of endometriosis." (PMID 40692689, 2025). "Higher amounts of C1, C3, and C5 have been detected in serum and peritoneal fluid of women with endometriosis." (PMID 40698088, 2025). "Increased amounts of C1, C3, and C5 were detected in serum and peritoneal fluid of women with endometriosis." (PMID 40698088, 2025). "Multi-omics analysis revealed a positive correlation between expression of central complement factors (C1S, C1QA, C1R, C3) and tissue factor (TF), indicating cross-interaction between complement and coagulation systems in the pathogenesis of endometriosis." (PMID 41488658, 2025). "Multi-omics analysis has revealed that up-regulated expression of complement (C1S, C1QA, C1R and C3) was positively correlated with tissue factor in endometriosis." (PMID 38012607, 2023). "It has been found that C3 inhibitors are probably a novel promising candidate used for endometriosis treatment theoretically in two pathways: One, blocking the initial inflammatory signal cascade and, two, relieving the inhibition of C3 on NK cytotoxicity." (PMID 37138868, 2023). "C3, another member of the complement system, has been reported to be upregulated in endometriosis and was also identified in our study as a common upregulated gene." (PMID 36339397, 2022). "Based on serum proteomic differential expression, a possible biomarker panel comprising zinc-alpha-2-glycoprotein, albumin, and complement C3 has been proposed for effective and non-invasive diagnosis of endometriosis." (PMID 32575462, 2020). "A similar situation could occur in endometriosis; increased C3 expression could contribute to inflammation-driven peritoneal tissue injury, which in turn would facilitate lesion implantation." (PMID 40698088, 2025). "Similarly, it has been reported that the abundance of C3 is significantly higher in peritoneal fluid and endometrial tissue in women with endometriosis." (PMID 39061077, 2024). "However, the complement C3 had a higher PF levels in the luteal than in the follicular phase of the menstrual cycle in both infertile and fertile patients with endometriosis." (PMID 29572748, 2018).
endometriosis (continued). "ELISA tests were performed on a cohort of endometriosis (n=100) and healthy patients (n=10) in order to confirm the differential expression of two proteins, complement C3 and human albumin identified through the proteomic approach described in Signorile and Baldi." (PMID 26759817, 2015). "Notably, as early as 1988, a study reported decreased levels of complement components C3 and C4 during the follicular phase of the menstrual cycle in patients with endometriosis, highlighting a potential link between complement activity and disease pathogenesis." (PMID 40692689, 2025). "Compared with the control group, high C3, VCAM1, ITGB2, and C3AR1 expression had statistical significance in endometriosis among the hub DEIRGs." (PMID 36660246, 2023). "Immunofluorescence confirmed that C3, C7, StAR and S100A10 were expressed more abundantly in endometriosis FBs." (PMID 34233737, 2021). "PPI analysis showed that CXCL12 interacts directly with complement C3 and C-C motif chemokine ligand 21 (CCL21), and a previous study showede CCL21 is up-regulated in endometriosis, which acts through inflammatory responses." (PMID 32439908, 2020). "The activity of both complement cascade members C3 and C4 was higher in the serum of women with endometriosis than in those without." (PMID 40698088, 2025). "This comprehensive study also showed that complement C3 levels are significantly higher in women with endometriosis than in those without endometriosis." (PMID 39061077, 2024). "Finally, compared with controls, C3 and VCAM1 were highly expressed in endometriosis tissue samples." (PMID 36660246, 2023). "Furthermore, women diagnosed with endometriosis showed significantly higher levels of C3 in peritoneal fluid and serum compared with women with no endometriosis." (PMID 41155459, 2025). "Finally, C3 and VCAM1 were highly expressed in endometriosis tissue samples compared with controls and may be potential biomarkers of endometriosis, which are helpful for the early diagnosis of endometriosis." (PMID 36660246, 2023). "In gastric cancer, C3 tissue deposition showed a negative correlation with plasma levels, highlighting the need for additional research to determine whether C3 is a suitable biomarker for endometriosis." (PMID 40698088, 2025).
glioma (19 papers, 2008 to 2025). A benign or malignant brain and spinal cord tumor that arises from glial cells (astrocytes, oligodendrocytes, ependymal cells). "Astrocytes isolated from the tumoral hemisphere of glioma-bearing mice revealed that KD up-regulated almost all the tested pro-inflammatory genes, together with C3, particularly enriched in inflammatory astrocytes." (PMID 39921723, 2025). "Elevated expression of both C3 and its receptor C3AR1 has been associated with poor survival outcomes in patients with glioma, particularly in IDH-wild-type GBM." (PMID 40843669, 2025). "Bulk RNA-Seq from TCGA data sets on GBM and low-grade glioma (TCGA_GBM and TCGA_GBMLGG) showed that C3 expression increased with glioma grade and IDH-WT status and was expressed at higher levels in GBM compared with nontumor brain." (PMID 39172519, 2024). "Complement component 3 (C3) and the receptor C3AR1 were both associated with aggressive disease and shorter survival in human glioma." (PMID 39172519, 2024). "While cumulative fold change of three peptides of VTN, PTGDS and C3 in GBM were found to be upregulated in GBM as compared to low grade glioma." (PMID 34055594, 2021). "A number of complement molecules like C1q, C5, and C3 are highly expressed in glioma cells, and are secreted into the microenvironment to participate in polarization of TAM, recruitment of peripheral monocyte and neoangiogenesis." (PMID 33869223, 2021). "Three peptides of 5 Proteins which includes APOA1, APOE, PTGDS, VTN and C3 were monitored for both Meningioma and Glioma samples." (PMID 34055594, 2021). "We observed that C3 is highly expressed in macrophages, and the glioma patients with higher expression of C3 tend to have significantly decreased survival days (P-value <0.05)." (PMID 31118022, 2019). "Moreover, C3 upregulation has been reported to be involved in recruiting myeloid-derived suppressor cells, maintaining the glioma stem cells pool and sustaining the neo-angiogenesis process." (PMID 35052804, 2022). "All gliomas and half of the BrM samples had comparably low levels of these cells (<15% of CD8+ T cells) and were defined as C3 low, while the other half of BrM tumors were highly infiltrated with C3 cells (>30% of CD8+ T cells) and were classified as C3 high." (PMID 37217652, 2023). "The lectin pathway has been shown to be activated in numerous glioma cell lines, where glioma cells expressing high levels of mannose-glycoproteins are easily bound by MBL, resulting in C3 and C4 activation." (PMID 31164885, 2019). "To determine whether presence of C3 can modulate tumor cell properties, we added serum-purified human C3 in serum-free culture medium of U3082MG, U3084MG, U3020MG, and U3065MG primary glioma cells." (PMID 39172519, 2024). "In G422 murine glioma models, it has been shown that PDT increases the ratio of CD4+/CD8+ lymphocytes and promotes TNF-α and IFN-γ release and promotes an anti-glioma response mediated by complement C3 and T-cells." (PMID 33540759, 2021). "In vivo, although the size of most recombinant C3-treated human xenogeneic graft gliomas was reduced markedly, no tumor disappeared as shown ex vivo." (PMID 18230152, 2008).
glioma (continued). "In vitro exposure to TGF-β increased C3, C3aR, and VEGF expressions in human TAM, but not in the U251MG glioma cell line." (PMID 37174113, 2023).
ischemia (18 papers, 2010 to 2025). A hypoperfusion of the BLOOD through an organ or tissue caused by a PATHOLOGIC CONSTRICTION or obstruction of its BLOOD VESSELS, or an absence of BLOOD CIRCULATION. "To address this topic and analyze the impact of the complement system on angiogenesis, we induced muscle ischemia in complement factor C3 deficient (C3−/−) and wildtype control mice by femoral artery ligation (FAL)." (PMID 34071589, 2021). "Elevated C3 in plasma from embolic ischemic stroke or cryptogenic stroke patients was associated with worse neurological outcomes 3 months and 2 years after ischemia onset." (PMID 31011487, 2019). "Although C3-deficient mice develop limited ischemia and ischemia/reperfusion injury, we found that C3aR1-deficient mice develop ischemia and ischemia/reperfusion injury, as also noted by others." (PMID 28928734, 2017). "Despite larger infarct, the C3 deficient mice had reduced neurogenic response in the ipsilesional subventricular zone and in the peri-infarct region after focal cerebral ischemia induced by middle cerebral artery occlusion at both 7 and 21 days after ischemia." (PMID 34379293, 2021). "Here we show that the complement peptide C3a exerts differential effects on the expression of Gfap, C3, Nes, Tnf and Il1b in naïve astrocytes, astrocytes after ischemia and astrocytes exposed to LPS." (PMID 36097103, 2023). "Intracellular C3 appears to be an important player in metabolic homeostasis during cardiac ischemia-reperfusion injury, which is in addition to the inflammatory effects associated with extracellular complement activation." (PMID 35432387, 2022). "In neonatal and adult rats subjected to hypoxia-ischemia surgery, the administration of CVF inhibited ischemia-induced C3 upregulation and reduced the brain infarct volume after 2 to 5 days of brain ischemia." (PMID 31011487, 2019). "In a rat model of liver ischemia/reperfusion, intravenous injection of sCR1 24 hours after ischemia reduced complement activity and C3 deposition on endothelial cells and ameliorated the reperfusion injury." (PMID 31011487, 2019). "We found that immune deficient Nude rats expressed unequivocal indicators of severe inflammation post-ischemia; presence of renal neutrophils infiltration and C3 complement component activation." (PMID 30148844, 2018). "We examined the deposition of C3 complement protein in mouse brain by means of immunohistochemistry in frozen sections of brain tissue obtained at 48 h post-ischemia." (PMID 20140243, 2010).
thrombosis (18 papers, 2014 to 2024). "C3 has been shown to bind fibrinogen and stabilize the clot by prolonging fibrinolysis, linking GPIIb/IIIa, fibrinogen, and C3 to thrombosis risk." (PMID 36591264, 2022). "This is in accordance with a study showing that C3-deficient mice have a reduced incidence of venous thrombosis, reduced platelet deposition and reduced platelet activation in vitro." (PMID 36591264, 2022). "Using C3−/− and C5−/− mice models, Subramaniam and colleagues (2017) reported that complement proteins participate in venous thrombosis after ligation of the inferior vena cava." (PMID 37543610, 2023). "Upstream blockade at the C3 level or a combination of C3 and C5 blockade could be a potential future avenue of research, especially in patients with ongoing thrombocytosis or thrombosis." (PMID 36788146, 2023). "Meanwhile, the SARS-CoV-2 virus may directly clip C3 to make C3a, namely complement activation, and then accelerates the development of neutrophils-induced thrombosis, coagulopathy, and tissue injury." (PMID 36123740, 2022). "Our study results revealed higher levels of mean plasma complement C4, C3, and ACLA-IgG in aPL-positive subjects with a history of thrombosis, but lower levels of complement C4, C3, and ACLA-IgG among aPL-positive subjects with SLE." (PMID 31134052, 2019). "It is important to recognize that the direction of changes for plasma protein levels of complement C3, C4, and ACLA-IgG among aPL-positive patients with SLE and with thrombosis or pregnancy morbidity are mostly opposite to each other." (PMID 31134052, 2019). "In another study investigating the significance of C3 and C4 in antiphospholipid syndrome, approximately, 40% lower levels of C4 (both C4A and C4B) were observed in thrombotic SLE patients with reference to thrombosis-free SLE patients." (PMID 35359932, 2022). "A “thrombotic composite score” consisting of PC4d, low C3, and LA is higher in SLE patients with history of thrombosis than in patients without this history." (PMID 39355252, 2024). "Although the serum levels of C3 and C4 in PAPS and in aPL positive carriers were reduced in comparison with healthy controls and patients with ITP or previous thrombosis without aPL, they were still within the normal range." (PMID 31031764, 2019). "Patients with thrombosis but without SLE (N = 126), and patients with SLE but without thrombosis (N = 182) had the greatest differences in mean protein levels of C3 (p = 2.6 × 10−6), C4 (p = 2.2 × 10−9) and ACLA-IgG (p = 1.2 × 10−5)." (PMID 31134052, 2019).
thrombotic microangiopathy (18 papers, 2016 to 2026). The syndromes of microangiopathic hemolytic anemia, thrombocytopenia, and variable signs of organ impairment, due to platelet aggregation in the microcirculation. "Subsequently, he underwent 2 kidney transplantations, which were lost because of acute rejection attributed to thrombotic microangiopathy and recurrence of IgA and C3 deposits, respectively." (PMID 40303201, 2025). "Immunofluorescence microscopy showed C3(+), Ig A(+) deposition in the mesangial region, which was pathologically consistent with thrombotic microangiopathy renal injury and Ig A deposition." (PMID 38965631, 2024). "Interestingly, mice deficient in hepatic FH exhibit low plasma FH and C3 as well as spontaneous mesangial C3 deposition, consistent with C3G, but develop severe C5-dependent thrombotic microangiopathy after a complement-activating trigger." (PMID 41550519, 2026). "However, Cfh–/–.FH Δ16-20 animals were unable to regulate C3 activation along renal endothelium and developed thrombotic microangiopathy." (PMID 33129896, 2021). "Therapeutic blockade or genetic deletion of C5, a protein downstream of C3 in the complement cascade, protected homozygous C3KI mice from thrombotic microangiopathy and aHUS." (PMID 30714990, 2019). "In this patient, thrombotic microangiopathy (TMA) was initially ruled out, followed by testing for a pathogenic variant in the C3 gene, which was negative." (PMID 40332152, 2025).
acute respiratory distress syndrome (17 papers, 2016 to 2025). Progressive and life-threatening pulmonary distress in the absence of an underlying pulmonary condition, usually following major trauma or surgery. "Activated C3 can exacerbate SARS-CoV-associated acute respiratory distress syndrome (ARDS)." (PMID 34135895, 2021). "A recent study on SARS-CoV infections has shown that C3 activation exacerbates acute respiratory distress syndrome (ARDS) which is associated with SARS-CoV." (PMID 34276659, 2021). "The C3-targeting drug candidate (AMY-101) has been successfully used to treat acute respiratory distress syndrome (ARDS)-like complement-mediated inflammatory damage of SARS-CoV-2 infection." (PMID 34067609, 2021). "C3 and complement activation have been recently involved in acute respiratory distress syndrome (ARDS) with systemic inflammation and lung neutrophilia." (PMID 32581077, 2020). "In addition, SARS-CoV-2 acts as a complement activator in a host so that C3 and C5 are activated, and ultimately induce acute respiratory distress syndrome (ARDS) in a host." (PMID 36289895, 2022).
allergic asthma (17 papers, 2005 to 2025). A asthma with a basis in a pathological type I hypersensitivity reaction. "The complement C3- and C5-derived anaphylatoxins C3a and C5a are known to contribute to the development of allergic asthma through their impact on dendritic cells and ILC2." (PMID 41148813, 2025). "In an allergic asthma mouse model, following the ovalbumin antigen challenge, an upregulation of complement components such as C1q and C3 was observed." (PMID 38892755, 2024). "We performed integrative analysis of three bulk gene expression profiles and identified five common IMR DEGs in childhood allergic asthma, including C3 and ALOX15, which are implicated in allergic asthma pathogenesis." (PMID 37123407, 2023). "Air-born allergens can cleave C3 or C5 directly through their protease activity resulting in the generation of C3a and C5a in vitro or in vivo during experimental and clinical allergic asthma." (PMID 28231307, 2017). "Complement activation in allergic asthma may occur through the classical, lectin, or alternative pathways; these pathways converge at the level of C3 activation." (PMID 17044927, 2006). "In addition, C3a and C5a modulates Th2 and Th17 immunity as the expression of IL17 by Th17 cell enhances C3 secretion by airway epithelial cells in severe allergic asthma." (PMID 26289385, 2015).